INS (insulin)
Diseases named in the same sentence as INS in open-access papers (continued):
Sharing a sentence is not in itself a finding about the gene and the disease.
amyloidosis (continued). "Both are a result of repeated insulin injections; however, insulin-derived amyloidosis typically presents as a firmer mass that does not regress." (PMID 39081432, 2024). "The patient presented in our case vignette represents non-systemic, AIns-type amyloidosis located at a site distant from the abdominal insulin pump access port." (PMID 39081432, 2024). "The high prevalence of amyloid deposits in diabetic patients treated with insulin and the low presence of amyloid in non-diabetics indicates that endogenous insulin reaction plays an essential role in the development of amyloid." (PMID 32503113, 2020). "INS, IL6 increases while APOE and APOA1 decrease the prediction of amyloidosis." (PMID 32753925, 2020). "Although the toxic amyloid deposit of insulin-derived amyloidosis was found in only one patient, no structural differences between toxic and non-toxic deposits were seen on histological and immunohistochemical studies." (PMID 31196059, 2019). "A limited number of studies have associated cutaneous amyloidosis with non-human insulin, such as porcine insulin, and there are even fewer published studies investigating amyloidosis with human insulin." (PMID 25009591, 2014). "Since we did not expect amyloidosis to be closely related to metabolism, we did not measure daily food intake or fasting plasma concentrations, and we did not perform indirect calorimetry, insulin tolerance tests, or glucose tolerance tests." (PMID 39699959, 2024). "However, when insulin is increased in the blood, IDE does not cleavage Aβ effectively and causes Aβ neurotoxicity, which eventually leads to AD amyloidosis." (PMID 36014555, 2022).
congestive heart failure (114 papers, 2008 to 2025). Failure of the heart to pump a sufficient amount of blood to meet the needs of the body tissues, resulting in tissue congestion and edema. "Although these agonists were beneficial in promoting insulin sensitization, these drugs are associated with many adverse effects, including weight gain, fluid retention, congestive heart failure, and bone fractures." (PMID 36928191, 2023). "Coenzyme Q10 was used to treat MELAS patients for a period of time, and it was found that it can promote insulin secretion, delay hearing loss, improve myopathy symptoms, congestive heart failure, and other complications." (PMID 36309717, 2022). "Possible risk factors identified included older age, preexisting congestive heart failure, severity of pneumonia, and the use of insulin by glucose sliding scales in hospitalized patients." (PMID 21738449, 2011). "CoQ10 is an antioxidant and mitochondrial cofactor that plays an important role in the mitochondrial respiratory chain, which may enhance insulin secretion, slow hearing loss, improve symptoms of myopathy and congestive heart failure in the setting of mitochondrial disease." (PMID 34899594, 2021). "We hypothesized that chronic treatment with GLP-1 or the exenatide analog AC3174 would improve cardiac function, cardiac remodeling, insulin sensitivity, and exercise capacity (EC) in rats with MI-induced chronic heart failure (CHF) caused by coronary artery ligation." (PMID 21080957, 2010). "They had worse cardiometabolic risk factors and complications, including CKD, retinopathy, CVD, and congestive heart failure, with a higher usage of insulin and RASi at baseline." (PMID 40954936, 2025). "A high degree of IR was observed in patients with chronic heart failure with a 58% reduced mean insulin sensitivity and a 131% increase in fasting insulin levels compared with data in the healthy control group of 20 patients." (PMID 39342254, 2024). "Some clinical factors were found to be associated with reduced access to kidney transplantation, including insulin treatment and congestive heart failure." (PMID 35488507, 2022). "In contrast, NDKD patients with congestive heart failure or those treated with insulin had a reduced chance of transplantation." (PMID 35488507, 2022). "Similar neuromodulatory effects of BDNF have been observed in congestive heart failure, insulin secretion after chronic exercise, and carbachol-induced contraction of intestinal longitudinal smooth muscle." (PMID 29540150, 2018). "Diazoxide suppresses insulin secretion and enhances glycogenolysis, but has severe adverse effects including sodium retention, congestive heart failure, or hirsutism." (PMID 26986124, 2016). "Furthermore, a 12-week Se supplementation for patients with congestive heart failure significantly reduced insulin concentrations and HOMA-IR." (PMID 40564877, 2025). "Previous studies have also shown that EAA supplementation improves CRF in ambulatory chronic heart failure patients, with this being explained by improved muscle aerobic metabolism, prevalence of muscle anabolic processes and reduction of insulin resistance." (PMID 28314994, 2017). "The insulin sensitizer, pioglitazone, has been demonstrated to improve glycemia in insulin-requiring T2DM patients; however use of this agent in this setting is associated with significant increased risk for congestive heart failure in addition to weight gain and edema." (PMID 26060825, 2015). "The prevalence of coronary atherosclerosis, congestive heart failure, atrial fibrillation, ischemic stroke, and peripheral arterial disease was lower in GLP1RA initiators compared with insulin initiators." (PMID 39860655, 2025). "For TyG, the proportions of indirect effects of insulin-mediated total CVD, congestive heart failure, and angina pectoris were 6.4, 10.2, and 10.6%, respectively." (PMID 38184598, 2024).
congestive heart failure (continued). "A subanalysis showed that the association between CABG and improved outcome was significant in both insulin- and oral antiglycemic treated patients, hypertensive and non-hypertensive patients, those with and without congestive heart failure, and regardless to the number of vessels involved." (PMID 36064537, 2022). "The insulin sensitisers are not approved for use in this country for treatment of NASH, and they should be used with caution in elderly people given the increased likelihood of coexisting medical conditions like congestive heart failure." (PMID 21918648, 2011). "The 5-factor modified frailty index (mFI-5) is one such frailty index that assesses 5 patient factors: functional status, history of diabetes mellitus (insulin and noninsulin dependent), chronic obstructive pulmonary disease (COPD), congestive heart failure (CHF), and hypertension." (PMID 40688349, 2025).
chronic obstructive pulmonary disease (107 papers, 2009 to 2026). A chronic and progressive lung disorder characterized by the loss of elasticity of the bronchial tree and the air sacs, destruction of the air sacs wall, thickening of the bronchial wall, and mucous accumulation in the bronchial tree. "The study concluded that among patients with T2DM receiving insulin, cardiac arrhythmias were common and were associated with glucose excursions." (PMID 39120245, 2024). "Moreover, the KCNJ11 E23K variant has been associated with T2DM due to its impact on beta cell function and insulin release, and it has also been linked to cardiac arrhythmias in diabetic patients." (PMID 40303486, 2025). "Equally crucial is the correction of potassium imbalance, which should be initiated prior to insulin therapy if serum potassium is below 3.3 mmol/L, to prevent life-threatening cardiac arrhythmias." (PMID 41149081, 2025). "Smoking cessation also improves respiratory function, including in patients with chronic obstructive pulmonary disease, or reduces insulin doses in diabetic patients." (PMID 37915359, 2023). "The patients with higher mean K+ levels had higher K+ variability, WBC counts, platelet counts, pH values, and creatinine levels as well as a higher prevalence of CKD, cardiac arrhythmia occurrence and insulin use." (PMID 35743452, 2022). "Mainly, they display slightly impaired insulin and somatostatin secretion, mild cardiac arrhythmia, and they are less prone to epilepsy." (PMID 31827421, 2019). "In fact, it is difficult to demonstrate how fatal cardiac arrhythmias are mediated during the insulin-induced severe hypoglycemic period." (PMID 30105256, 2018). "We also find that glimepiride and tolbutamide, two T2D drugs that lower blood glucose by increasing the secretion of insulin, are proximal to cardiac arrhythmia (zc=−3.6 and zc =−2.3, respectively)." (PMID 26831545, 2016). "Different, non-mutually exclusive, mechanisms might mediate the relationship between insulin therapy and cardiac arrhythmias." (PMID 36237914, 2022). "Alterations in mitochondrial distribution, morphology, and function are present in atrophic muscles in aging, muscle disuse, burn injury, intensive care unit-acquired weakness, insulin resistance chronic obstructive pulmonary disease (COPD), cancer cachexia, and different neuromuscular disorders." (PMID 33078210, 2021). "Among the DM patients, predictors for late mortality were insulin treatment (HR 1.76 95% CI 1.05–2.94, p = 0.033), older age, with 6% increased odds for mortality per 1-year increment in age (p < 0.001), and chronic obstructive pulmonary disease (HR 1.89 95% CI 1.12–3.19, p = 0.018)." (PMID 30876424, 2019). "The joint effect of insulin and chronic obstructive pulmonary disease was also evaluated." (PMID 31354621, 2019). "Joint effects of human insulin and chronic obstructive pulmonary disease on lung cancer." (PMID 31354621, 2019). "Hence patients with serum potassium levels <3.3mmol/L need initial management with fluid resuscitation and potassium replacement, whilst delaying commencement of insulin until after potassium levels are above 3.3 mmol/L, to avoid cardiac arrhythmias, arrest, and respiratory muscle weakness." (PMID 28659865, 2017). "A 60-year-old woman, with a medical history of heavy smoking, asthma-chronic obstructive pulmonary disease (COPD) overlap syndrome, Child-Pugh A alcoholic liver cirrhosis, type 2 diabetes mellitus treated with insulin, and arterial hypertension." (PMID 40688960, 2025). "Cardiac arrhythmia and sudden death can occur; so, cardiac monitoring should be performed, calcium gluconate may need to be administrated, and potassium‐lowering strategies such as glucose/insulin infusion, beta‐agonist inhalation, and oral potassium‐binding agents may also be used." (PMID 35846936, 2022).
chronic obstructive pulmonary disease (continued). "Chronic obstructive pulmonary disease (COPD) combines the deleterious effects of chronic hypoxia, chronic inflammation, insulin-resistance, increased energy expenditure, muscle wasting, and exercise deconditioning." (PMID 24701566, 2014). "DM, a metabolic disorder characterized by high blood sugar levels resulting from either insulin resistance or a lack of insulin production, intertwines with AF, a cardiac arrhythmia marked by irregular and rapid heartbeats resulting from abnormal electrical impulses in the atria." (PMID 37885547, 2023). "Compared to patients without insulin use and without chronic obstructive pulmonary disease, insulin users who also had chronic obstructive pulmonary disease had the highest risk of lung cancer (adjusted hazard ratio: 1.891, 95% confidence interval: 1.767–2.024)." (PMID 31354621, 2019). "For example, patients with kidney disease, chronic obstructive pulmonary disease (COPD), and cardiovascular disease (CVD) rely on dialysis and oxygen machines that require electricity and diabetics must refrigerate their insulin." (PMID 31921733, 2019). "Compared to patients without MACEs, theMACEs group showed higher rates of AMI, chronic obstructive pulmonary disease(COPD) and DM, increased use of insulin and diuretics, but lower aspirinutilization at discharge." (PMID 40776972, 2025).
lung carcinoma (106 papers, 2006 to 2025). "By analyzing medical records from over a million patients, the researchers aim to identify which medications are associated with a reduced risk of lung cancer compared with insulin." (PMID 39001440, 2024). "Enhanced inflammatory responses in insulin-resistant states have been associated with the progression of lung cancer." (PMID 38449844, 2024). "Another study found that use of insulin, glinides, and sulfonylureas increased the risk for gastrointestinal and lung cancers." (PMID 35244142, 2022). "A 9.6-year case-cohort study of Finnish men showed that higher fasting insulin level was associated with an increased lung cancer risk." (PMID 35256755, 2022). "Exposure either to metformin or to insulin was associated with a lower risk of lung cancer-specific mortality, and this approached statistical significance (HR 0.82, 95% CI 0.72–92 for metformin and HR 0.65, 95% CI 0.44–95 for insulin)." (PMID 32156062, 2020). "This is the first time to discover that silencing of ZNF322A is capable to mediate the regulation of insulin signal transduction pathway and caused glucose starvation in lung cancer cells." (PMID 32576196, 2020). "Insulin treatment in our study was significantly associated with a lower risk of lung cancer-specific mortality and showed a tendency towards decreased overall mortality." (PMID 32156062, 2020). "In conclusion, this population-based retrospective cohort study in Taiwan suggests an association between human insulin use and lung cancer." (PMID 31354621, 2019). "The hazard ratios for the different subgroups of the three dose–response parameters all suggested a significantly higher risk of lung cancer associated with insulin use (P trend < 0.0001)." (PMID 31354621, 2019). "The adjusted hazard ratio for ever-users vs. never-users was 1.545 (95% confidence interval: 1.478–1.614), suggesting a significantly higher risk of lung cancer associated with human insulin use." (PMID 31354621, 2019). "Because the use of human insulin through inhalation has been shown to increase the risk of lung cancer, the prolonged use of insulin via subcutaneous injection is highly possible." (PMID 31354621, 2019). "Our results lend further support to epidemiological studies showing an increased lung cancer risk for the effect of reduced lipid levels and elevated circulating insulin." (PMID 28594918, 2017). "Our results are consistent with a causal role of fasting insulin and low-density lipoprotein cholesterol in lung cancer etiology, as well as for BMI in squamous cell and small cell carcinoma." (PMID 28594918, 2017). "Among glucose and insulin parameters, fasting insulin was associated with an increased risk in overall lung cancer (OR [95%CI] = 1.63 [1.25–2.13] per each SD increase [44.4 pmol/l])." (PMID 28594918, 2017). "Observational studies have indicated an inverse relationship for both body mass index (BMI) and lipid levels, as well as a positive correlation with dietary glycemic index and insulin levels, with lung cancer risk." (PMID 28594918, 2017). "Our results are also consistent with observational studies that indicate an inverse relationship between lipid levels and lung cancer risk, and an increasing risk caused by elevated fasting insulin levels." (PMID 28594918, 2017). "Further evaluation of different forms of exogenous insulin is required to better understand this possible association with lung cancer." (PMID 24924771, 2014). "The result of studies that adjusted for smoking illustrated that insulin still increased lung cancer risk (OR 1.30, 95% CI 1.09 to 1.51)." (PMID 24924771, 2014). "Patients treated with metformin are at a lower risk of colorectal and liver cancers, compared to those receiving either insulin or sulphonylurea, and at a lower risk of breast and lung cancer, compared to those receiving sulphonylureas." (PMID 22719752, 2012). "Insulin was significantly associated with all three types of lung cancer." (PMID 40017690, 2025).
lung carcinoma (continued). "Similarly, smaller hospital-based studies have linked elevated HOMA-IR or fasting insulin levels to greater lung cancer risk and mortality." (PMID 41427040, 2025). "In addition, glucose-lowering medications show inconsistent associations with lung cancer risk, that is, an apparent decreased risk with metformin and increased risk with insulin and insulin secretagogues, with potential for confounding by indication." (PMID 38902745, 2024). "Meanwhile, a previous study has reported that higher fasting insulin could increase the risk of lung cancer." (PMID 34662362, 2021). "The mechanisms of insulin-related lung cancer risk remain to be investigated." (PMID 31354621, 2019). "There was also evidence that low-density lipoprotein cholesterol was inversely associated with lung cancer overall risk (OR [95%CI] = 0.90 [0.84–0.97] per SD of 38 mg/dl), while fasting insulin was positively associated (OR [95%CI] = 1.63 [1.25–2.13] per SD of 44.4 pmol/l)." (PMID 28594918, 2017). "All hazard ratios favored a lower risk of lung cancer associated with metformin use, even though the P-values were not significant for the subgroups who had been followed up for ≥5 years or had been using insulin, acarbose or rosiglitazone." (PMID 28456789, 2017). "Additionally, we found consistent evidence of a positive association between fasting insulin and overall lung cancer risk, as well as an inverse relationship between LDL levels and lung cancer risk." (PMID 28594918, 2017). "Insulin use may be associated with 23% increased lung cancer risk, and the effect persisted in studies adjusted for smoking." (PMID 24924771, 2014). "Higher lung cancer risk was related to insulin (OR 1.23, 95% CI 1.10 to 1.35)." (PMID 24924771, 2014). "Thus, the association between fasting insulin and lung cancer should be further explored." (PMID 34662362, 2021). "Since we hypothesized that mutations at or around the YXXM motifs of IRS1 mayimpact insulin signaling and the phenotype of lung cancer, we isolated thegenomic DNA from 42 tumor and 40 normal lung tissues of NSCLC patients andsequenced the coding region of IRS1." (PMID 30807634, 2019). "Therefore, if smoking played a confounding effect in the present study, this might only have underestimated the hazard ratio of lung cancer associated with insulin use." (PMID 31354621, 2019). "Notably, intracellular presence of insulin is associated with adverse prognosis in human lung adenocarcinoma; High circulating IGF-1 levels are associated with increased risk of lung cancer, and inhibition of insulin/IGF-1 signaling inhibits growth of lung cancer cells." (PMID 20642846, 2010). "Insulin inhalers were removed from the market in October 2007 because of worries regarding lung cancer." (PMID 40574088, 2025). "Klotho can inhibit the IGF-1/insulin and Wnt/β-catenin signaling pathways, promoting autophagy and apoptosis of lung cancer cells, thus exerting an inhibitory effect on tumor growth." (PMID 38287280, 2024). "Research has demonstrated that engaging in moderate exercise can enhance insulin sensitivity, lower insulin resistance, and subsequently decrease the likelihood of developing lung cancer." (PMID 38449844, 2024). "Compared to other insulin delivery approaches, the development of microfluidic technologies for inhaled insulin is rare, possibly owing to previous finding that use of inhaled insulin is positively correlated with lung cancer." (PMID 38509342, 2024). "Although the fasting insulin level was lower in the lung cancer group than in the non-lung cancer group, the difference between the two groups was insignificant." (PMID 38468345, 2024). "Microfluidic platforms for inhaled insulin are rare, likely due to established correlations between inhaled insulin and lung cancer." (PMID 38509342, 2024). "This suggests that, in the state of insulin resistance, excessive insulin accumulates extracellularly and promotes the development of lung cancer." (PMID 38449844, 2024).